GPC2 (glypican 2)
Diseases named in the same sentence as GPC2 in open-access papers (continued):
Sharing a sentence is not in itself a finding about the gene and the disease.
cancer (29 papers, 2012 to 2025). A tumor composed of atypical neoplastic, often pleomorphic cells that invade other tissues. "Our result of CIBERSORT revealed that for most types of cancer, the association between levels of immune cell infiltration and GPC2 expression was significant." (PMID 35345673, 2022). "GPC2 showed high diagnostic accuracy in 6 forms of cancer (AUC: 1.0–0.9), and it is worth noting that 1.0 was reached in CHOL." (PMID 35345673, 2022). "Aiming to investigate the association between GPC2 expression level and prognosis, we performed a survival association analysis for each cancer, concentrating on OS, DSS, and PFI." (PMID 35345673, 2022). "There is a discovery that GPC2 can be employed as a diagnostic, prognostic, and immunological predictor of generalized cancers." (PMID 35345673, 2022). "demonstrate that GPC2 could sreve as a Potential prognostic, diagnostic, and immunological biomarker in pan-cancer." (PMID 37377953, 2023). "GPC2 expression was significantly upregulated in 12 early-stage cancers compared with normal tissues.GPC2 displayed high diagnostic value (AUC > 0.90) for 6 cancer types, moderate diagnostic value (AUC > 0.70) in 16 cancer types, and low diagnostic value (AUC > 0.50) in 7 cancer types." (PMID 36980276, 2023). "In this study, we generated T cells with engineered AbTCRs that include a synthetic antibody γδ TCR and an antibody co-stimulatory domain directing T cells to recognize and eliminate GPC2-expressing cancer cells." (PMID 41027430, 2025). "In cancers where adequate normal tissue data was available, GPC2 expression differed significantly in 15 cancer types compared to normal tissue." (PMID 38045624, 2023). "An organized evaluation of the impact of each individual GPC in cancer has only been performed for glypican 2 (GPC2)." (PMID 36944188, 2023). "With the analysis and comparison of the expression of GPC2 in types of malignancies, we further conducted immune infiltration levels, co-expression analysis of immune-related genes with GPC2, and DNA methylation across 33 types of cancer." (PMID 35345673, 2022). "Except for cancers with no normal tissue data or only an insufficient number of normal tissue samples, our results detected the significant differences of GPC2 expression between tumors and normal tissues of 20 forms of cancer." (PMID 35345673, 2022). "On the other hand, GPC2 was a low-risk factor in PAAD, LAML, BLCA, LGG, HNSC, THYM, and ESCA, while it was a high-risk factor in other types of cancer, especially PRAD (hazard ratio = 10.20)." (PMID 35345673, 2022). "By and large, these findings confirm that GPC2 expression is upregulated in a variety of cancers, suggesting that the prospect of GPC2 in cancer diagnosis is worth looking forward to." (PMID 35345673, 2022). "Analysis showed an early elevation of GPC2 in 16 of the 17 cancers in which staging and normal control samples were collected." (PMID 35345673, 2022). "We also made a comparison between cancer and paired normal samples on GPC2 expression levels in 33 cancers, based on TCGA data." (PMID 35345673, 2022). "Immunohistochemical analysis confirmed higher levels of GPC2 protein at the protein level in almost all cancers." (PMID 35345673, 2022). "For the time being, the early cancer detection is of great clinical significance, to push back the frontier of the early cancer detection; thereby, we explored the differential expression of GPC2 in the samples marked with cancer staging information." (PMID 35345673, 2022). "The UALCAN online tool provided a platform for us to investigate promoter methylation levels of GPC2 among groups of patients and normals according to different cancers." (PMID 35345673, 2022). "To summarize, we successfully identified a mAb, CT3, that selectively binds to GPC2 in human cancer cells with undetectable reactivity in almost all human normal tissues." (PMID 34195677, 2021).
cancer (continued). "Using RNA sequencing (RNA-seq) analysis, we show that exon 3 and exons 7–10 of GPC2 are expressed in cancer but are minimally expressed in normal tissues." (PMID 34195677, 2021). "From this view, the highest value targets are MCAM and GPC2, which are expressed in the Top 25 for eight different cancers." (PMID 23251904, 2012). "Pan-cancer studies on GPC2 have determined its early diagnostic value in 16 kinds of tumors where GPC2 exhibits positive or negative associations with the cancer prognosis." (PMID 38612755, 2024). "In addition, GPC2 expression was significantly increased in 16 cancers in paired sample expression differential analysis." (PMID 35345673, 2022). "Whereafter, we ranked GPC2 expression levels in various cancers from lowest to highest." (PMID 35345673, 2022). "Through pan-cancer analysis, we discovered and verified that GPC2 might be useful in cancer detection for the first time." (PMID 35345673, 2022). "Next, we used CT3 to validate GPC2 protein expression in pediatric cancers." (PMID 34195677, 2021). "Moreover, researches showed that enforced expression of GPC2 contributed to malignant behaviors of cancer cells and might act as potential cancer therapeutic targets." (PMID 39014225, 2024). "Additionally, GPC2 gene expression has a correlation with DNA methylation in 20 types of cancers." (PMID 35345673, 2022). "GPC2 belongs to the GPC (GPC1-6) family, which plays a variety of roles in growth factor signaling and cancer cell growth, regulates the growth and development process of the body." (PMID 35795788, 2022). "MDK (a cytokine and growth factor with complex biological functions involved in cancer development and progression), together with its two receptors (SDC1 and GPC2) were highly expressed in the B-cells of BCP-ALL samples." (PMID 33777800, 2021). "Here, a cancer-wide GPC expression study, using clinical cancer patient data in The Cancer Genome Atlas, reveals net upregulation of GPC1 and GPC2 in primary solid tumors, whereas GPC3, GPC5 and GPC6 display lowered expression pattern compared to normal tissues." (PMID 36944188, 2023). "There are growing reports using nanobody-based immunotoxins to treat cancers by targeting a variety of antigens such as glypican-3, glypican-2, EGFR, HER2, VEGFR2, CD7 and CD38, which indicates the great potential of nanobody-based immunotoxins for cancer therapy." (PMID 36435809, 2022). "Except for those cancers in which no normal tissue data were available or only had very few normal samples, it was detected that the expression of GPC2 in 21 types of cancer was significantly different from that in normal tissue." (PMID 35345673, 2022). "Similarly, testis-restricted targets such as SPA17, TEX14, LAMA1, SMOC1, TNFAIP6, GPC2, and COL20A1 may also be leveraged for their cancer-specificity." (PMID 38702309, 2024). "Compared with GPC-1, GPC-2, GPC-3, and GPC-5, few studies have investigated the mechanism and prognostic significance of GPC-4 and GPC-6 expressions at the mRNA level in malignant tumors, and no related reports have been found in HCC." (PMID 33902495, 2021).
GPC2 also shares sentences with these, for which no sentence is quoted: Alzheimer disease (2 papers); breast carcinoma (2); lung carcinoma (2); rhabdomyosarcoma (2); sarcoma (2); acute myeloid leukemia (1); central nervous system diseases (1); colonic polyps (1); depression (1); digestive system tumors (1); endometriosis (1); esophagogastric adenocarcinoma (1); Ewing sarcoma (1); female infertility (1); infection (1); lentivirus infection (1); lymph node metastasis (1); melanoma (1); mesothelioma (1); prostate (1); skin cutaneous melanoma (1); thymoma (1); uveal melanoma (1).